RAC1 (Rac family small GTPase 1)
Diseases named in the same sentence as RAC1 in open-access papers (continued):
Sharing a sentence is not in itself a finding about the gene and the disease.
acute lymphoblastic leukemia (1 paper, 2022). Leukemia with an acute onset, characterized by the presence of lymphoblasts in the bone marrow and the peripheral blood. "At least in acute lymphoblastic leukemia, Rac1 activation is observed in response to the CXCL12/CXCR4 axis." (PMID 36009428, 2022).
adenomyosis (1 paper, 2023). The growth of endometrial tissue inside the muscular wall of the uterine corpus. "Some researchers found that rhein can significantly reduce the abnormal endometrial proliferation of adenomyosis, in a dose-dependent manner, attributing to the suppressed Rac1." (PMID 36969843, 2023).
allergic rhinitis (1 paper, 2025). Inflammation of the nasal mucous membranes caused by an IgE-mediated response to external allergens. "By stably binding to AMPK1, SYK, and RAC1, these components may inhibit the activation and migration of inflammatory cells and reduce the release of inflammatory mediators, thereby alleviating the symptoms of allergic rhinitis." (PMID 40732349, 2025).
alopecia (1 paper, 2022). Hair loss usually from the scalp. "The down-regulation of RAC1 may be the cause of alopecia in giant pandas." (PMID 35413801, 2022).
alveolar rhabdomyosarcoma (1 paper, 2024). A rapidly growing malignant mesenchymal neoplasm. "G9a knockdown (shG9a) or activity inhibition in alveolar rhabdomyosarcoma (ARMS) upregulated PTEN, reduced phosphorylation of AKT, and decreased RAC1 activity, resulting in a decrease in cell proliferation and defective cell migration." (PMID 40396280, 2024).
ampullary adenocarcinoma (1 paper, 2015). "The reciprocal expression of nestin and RAC1 were explored using a cDNA microarray analysis in the early stages of ampullary adenocarcinoma." (PMID 25371063, 2015). "Increased level of CDK5 with simultaneously decreased expression of Rac1 was detected by western blotting of ampullary adenocarcinoma in patients without cancer recurrence." (PMID 25371063, 2015).
ampullary cancer (1 paper, 2015). "The result of the western blotting confirmed that the RAC1 pathway was suppressed in certain patients with early ampullary cancer." (PMID 25371063, 2015). "The RAC1 pathway was suppressed among certain patients with early ampullary cancer." (PMID 25371063, 2015). "Lacking adequate neovascularization, hypoxia may develop during growth of a primary tumor in early ampullary cancer; thus, nestin/CDK5 temporarily suppresses RAC1." (PMID 25371063, 2015).
anaplastic thyroid cancers (1 paper, 2022). "In anaplastic thyroid cancers, Lee demonstrated that DSG2 knockdown induced cell motility and invasiveness through the cMet/Src/Rac1 signaling axis and that targeting cMet inhibited DSG2 knockdown-induced distant metastasis in mouse xenografts." (PMID 35345582, 2022).
ankylosing spondylitis (1 paper, 2022). An autoimmune chronic inflammatory disorder characterized by inflammation in the vertebral joints of the spine and sacroiliac joints. "However, Rac1 seems to be an important player concerning OPC migration, which could also be confirmed in a model of Ankylosing spondylitis (AS) and so we conclude that inhibition of RhoA released Rac1 from blockage by RhoA and therefore intensified the motility of OPCs." (PMID 36531963, 2022).
Anophthalmia (1 paper, 2019). Absence of the globe or eyeball. "A further defect observed in Grhl3Cre-Rac1 mutant fetuses was occasional microphthalmia or anophthalmia, but this occurred at low frequency and was not analysed further." (PMID 31628096, 2019).
arteriosclerosis obliterans (1 paper, 2022). Common occlusive arterial disease which is caused by atherosclerosis. "RAC1 promotes CD4+ T cell migration in arteriosclerosis obliterans." (PMID 36211372, 2022).
artery disease (1 paper, 2017). "Finally, we tested whether Rac1 inhibition is able to improve endothelial function of portions of saphenous veins used as conduits for surgical revascularization (bypass) of patients with peripheral ischemia due to severe artery disease." (PMID 28246076, 2017).
asbestosis (1 paper, 2015). A lung disorder caused by inhalation of asbestos fibers. "These investigators showed that mitochondrial Rac-1 levels are elevated in AM from patients with asbestosis, that Rac-1 augments asbestos-induced AM H2O2 production, and that ROS production is reduced by knockdown of the iron-sulfur complex III in the mitochondrial ETC." (PMID 26370974, 2015).
astroglioma (1 paper, 2014). "Previous studies in astroglioma cell lines also showed that Rac1 is activated during HIV-induced cell fusion and this is mediated by co-receptors and cytoskeletal actin, and Rac1 inhibitors decreased adhesion of U937 cells to endothelial cells." (PMID 24571616, 2014).
bacteremia (1 paper, 2025). "The remaining ten patients with bacteremia exhibited either neutrophilia or pancytopenia and displayed normal to below-normal Rac1 GTPase activity, which is consistent with bacteria-induced immunosuppression." (PMID 40041147, 2025). "Our findings indicated that 18 of the 28 patients with bacteremia showed an increase of ≥ 3-fold in Rac1•GTP levels compared to the controls." (PMID 40041147, 2025). "Elevated or suppressed levels of Rac1•GTP, along with a complete blood cell count, can help identify the species causing bacteremia." (PMID 40041147, 2025). "Our study aimed to determine if multivariate analysis of immune variables based on complete white blood cell counts and Rac1•GTP levels in innate and adaptive immune cells—are adequate to identify the bacterial species associated with bacteremia in various patients." (PMID 40041147, 2025).
bacterial pneumonia (1 paper, 2022). Acute infection of the lung parenchyma caused by bacteria (e.g., Streptococcus pneumoniae, Haemophilus influenzae, Chlamydia pneumoniae, Mycoplasma pneumoniae, and Legionella pneumophila). "We showed that loss of PAR2 expression and consequent impairment of Rac1 activity compromised PA clearance in the PAR2-null lungs, resulting in ALI and death from bacterial pneumonia." (PMID 36204227, 2022).
basophilic leukemia (1 paper, 2012). "In some cell types, ERK is a downstream target of the Rac1 signaling cascade, such as in rat basophilic leukemia mast cells, and inactivation of Rac1 was sufficient to suppress ERK activation induced by eotaxin." (PMID 22701712, 2012).
bone cancer (1 paper, 2019). A primary or metastatic malignant neoplasm affecting the bone or articular cartilage. "Subtoxic doses of eIF2α phosphatase GADD34/PP1c inhibitors guanabenz or salubrinal reduce breast and bone cancer cell migration/invasion through the reduction of SRC and RAC1 activity and through the modulation of MMP13 expression (for salubrinal)." (PMID 31064137, 2019).
Burkitt lymphoma (1 paper, 2018). A rare form of malignant mature B-cell non-Hodgkin lymphoma. "In Namalwa cells, a cell line derived from Burkitt’s lymphoma, Rac1 activation is prevented through sequestration by association with the formin, FMNL1." (PMID 30558116, 2018). "In a Burkitt’s lymphoma cell line (BL-41), Rac1 was found to induce the phosphorylation of Bad at S75 (corresponds to murine Ser112), which keeps Bad inactive and prevents its pro-apoptotic properties." (PMID 30558116, 2018).
Cachexia (1 paper, 2024). Severe weight loss, wasting of muscle, loss of appetite, and general debility related to a chronic disease. "To investigate whether Rac1 inhibition exerted similar beneficial effects on CAC as RK, we treated C26 mice daily with NSC23766 or RK starting 2 days after cachexia onset." (PMID 38302863, 2024).
calcification (1 paper, 2023). Process by which organic tissue becomes hardened by the physiologic deposit of calcium salts. "We have previously demonstrated a potential mechanistic pathway of statin-induced, Rac1-dependent atherosclerotic vascular calcification." (PMID 37498869, 2023).
cervical tumor (1 paper, 2015). "As Rac1 and Rap1 regulate migration and metastasis in H/R-experienced cancer cells, we used HeLa cervical tumor cells and Tβ4-transgenic (Tg) mice to assess the effect of Tβ4 on Rac1- and Rap1-GTPase." (PMID 25888632, 2015).
choriocarcinoma (1 paper, 2021). An aggressive malignant tumor arising from trophoblastic cells.
chronic myelomonocytic leukemia (1 paper, 2021). A myelodysplastic/myeloproliferative neoplasm which is characterized by persistent monocytosis, absence of a Philadelphia chromosome and BCR/ABL fusion gene, fewer than 20 percent blasts in the bone marrow and blood, myelodysplasia, and absence of PDGFRA or PDGFRB rearrangement. "This important role of the NLRP3 inflammasome in the pathogenesis of myeloid malignancies and the newly identified KRAS/RAC1/ROS/NLRP3/IL-1β axis has been demonstrated in chronic myelomonocytic leukemia (CMML), juvenile myelomonocytic leukemia (JNNL) and AML patients harboring the KRAS mutation." (PMID 33525345, 2021).
Cirrhosis (1 paper, 2015). A chronic disorder of the liver in which liver tissue becomes scarred and is partially replaced by regenerative nodules and fibrotic tissue resulting in loss of liver function. "Blockade of Rac1/JNK activation impeded gankyrin-mediated hepatocytic malignant transformation, indicating the combined inhibition of gankyrin and Rac1/JNK as a potential prevention mechanism for cirrhosis transition." (PMID 25950481, 2015).
clear cell carcinoma (1 paper, 2022). "The in vitro study showed that knockdown of MICAL1 led to a decreased Rac1 activation and migration of clear cell carcinoma cells." (PMID 36575439, 2022).
cocaine addiction (1 paper, 2015). "Studies have shown that Rac1 is involved in cocaine addiction." (PMID 26582975, 2015).
cognitive (1 paper, 2021). "In conclusion, DEX may relieve oxidative stress damage in the hippocampus, neuronal damage, and inflammatory response in the hippocampal CA1 region of SD rats via the Rac1/AKT/NF-κB pathway, thereby improving the cognitive dysfunction." (PMID 34622713, 2021).
complication (1 paper, 2017). Any disease or disorder that occurs during the course of, or because of, another disease, treatment, or procedure. "GLP-1 ameliorated high-glucose-induced oxidative stress by inhibiting NOX4, p47phox, and Rac-1 expression and translocation of p47phox, suggesting its clinical usefulness in diabetic vascular complications." (PMID 28808291, 2017).
congenital heart defects (1 paper, 2024). "Interestingly in humans, pathogenic variants in both RAC1 and CDC42 have been associated with malformation syndromes, including congenital heart defects." (PMID 38501224, 2024).
demyelinating disease (1 paper, 2022). A broad group of disorders that affect the myelin sheaths that cover the neurons. "The study of the GEF-Cdc42/Rac1 signaling pathway provides new ideas for the use of catalpol to treat demyelinating diseases and promote myelin regeneration." (PMID 36482934, 2022). "We interpret our findings to indicate that catalpol can positively facilitate OL regeneration by promoting the activation of the GEF-Cdc42/Rac1 signaling pathway, suggesting that this drug is a promising candidate for the clinical treatment of demyelinating diseases." (PMID 36482934, 2022).
desmoplastic melanoma (1 paper, 2022). A melanoma of the skin characterized by a proliferation of atypical spindled melanocytes in the dermis, in a background of abundant collagen. "Tumors associated with high UV exposure, such as melanoma in situ, lentigo maligna, and desmoplastic melanoma, are most commonly related to mutations in BRAF (other than p.V600E), neurofibromatosis type 1 (NF1), and Ras-related C3 botulinum toxin substrate 1 (RAC1)." (PMID 36289768, 2022).
developmental and epileptic encephalopathy 23 (1 paper, 2022). "Dedicator of cytokinesis protein 7 (DOCK7), which is localized to the developing axons, activates Rac1 and Rac3 small GTPases and regulates neuronal polarity; moreover, its variants cause developmental and epileptic encephalopathy 23 (DEE23)." (PMID 36030824, 2022).
diabetic neuropathy (1 paper, 2023). A chronic, pathological complication associated with diabetes mellitus, where nerve damages are incurred due to diabetic microvascular injury involving small blood vessels that supply these nerves, resulting in peripheral and/or autonomic nerve dysfunction. "We revealed an association of the genotype rs7784465-T/C of the RAC1 gene with an increased risk of diabetic neuropathy in females." (PMID 36979960, 2023).
Down syndrome (1 paper, 2013). "For example, RAC1 partners with oligophrenin-1 and synaptojanin which have been linked to X-linked intellectual disability and Down’s syndrome, respectively." (PMID 23803181, 2013).
Duane retraction syndrome (1 paper, 2019). Duane retraction syndrome (DRS) is a congenital form of strabismus characterized by horizontal eye movement limitation, globe retraction and palpebral fissure narrowing in attempted adduction. "Two related studies, have demonstrated that several missense mutations leading to enhanced dimerization and Rac1-GAP activity of α2-chimaerin causes Duane’s retraction syndrome (DRS) with strabismus phenotype." (PMID 30934641, 2019).
Duchenne muscular dystrophy (1 paper, 2023). Duchenne muscular dystrophy (DMD) is a neuromuscular disease characterized by rapidly progressive muscle weakness and wasting due to degeneration of skeletal, smooth and cardiac muscle. "In Duchenne muscular dystrophy (DMD), a progressive X-linked neuromuscular disorder, DOCK3 expression is increased; however, the increased expression is observed along with a subsequent decrease in the levels of activated RAC1 due to skeletal myofiber membrane instability." (PMID 37895289, 2023).
dyslexia (1 paper, 2019). A learning disorder characterized by an impairment in processing written words. "DOCK4 (dedicator for cytokinesis 4), a guanine nucleotide exchange factor (GEF) for the small GTPase Rac1, is one of few genes that are associated with both ASD and dyslexia." (PMID 32009906, 2019).
endometrioid carcinoma (1 paper, 2025). "In addition to HNSCC, RAC1-A159V hotspot mutation has also been identified in endometrioid carcinoma (TCGA-BG-A0MG-01, GENIE-MSK-P-0044987-T01-IM6, and GENIE-MSK-P-0067212-T01-IM7)." (PMID 39941730, 2025).
endometritis (1 paper, 2020). An acute or chronic, usually bacterial infectious process affecting the endometrium. "The pro-inflammatory cytokines' inhibitory expression was adversely associated with the expression of the miR-488 and showed the suppression of the expression of Rac1, and an inhibitory AKT/NF-kB signal mediated LPS activation of endometritis." (PMID 33426032, 2020). "The miR-488 control of Rac1/AKT/NF-κB signaling inflammatory pathways in other inflammatory diseases, including endometritis, needs further exploration." (PMID 33426032, 2020).
epidermodysplasia verruciformis (1 paper, 2016). A rare inherited genodermatosis characterized by chronic infection with human papillomavirus (HPV) leading to polymorphous cutaneous lesions and high risk of developing non melanoma skin cancer. "While HPV-8 was found to be involved in the development of SCCs in sun exposed skin of patients with epidermodysplasia verruciformis, over-expression and activation of Rac1 have been reported in SCCs of mucosa and cornified skin." (PMID 27506937, 2016).
experimental autoimmune encephalomyelitis (1 paper, 2016). An autoimmune demyelinating disease of the central nervous system that is produced experimentally in animals by the injection of homogenized brain or spinal cord in Freund's adjuvant. "Whereas Tiam1 genetic deficiency weakens IL-17A expression partially and inhibits the development of experimental autoimmune encephalomyelitis (EAE), deletion of Rac1 in T cells exhibits more robust effects on Th17 cells and EAE." (PMID 27725632, 2016).
fronto-temporal dementia (1 paper, 2018). "We showed here that Rac1 increased in AD patients with MMSE< 18 and, in a recent work, that Cdc42 decreased in fronto-temporal dementia patients." (PMID 30005699, 2018).
fungal infection (1 paper, 2015). "In addition, Ly-GDI associates with CARD9, a caspase-recruitment domain (CARD)-containing protein, in phagosomes after bacterial and fungal infection, and binding of CARD9 suppressed LyGDI-mediated inhibition of the GTPase Rac1, thereby leading to bacterial killing in macrophages." (PMID 26469087, 2015).
gastric tumor (1 paper, 2024). "The correlation between the expression of ITGB6 and Rac1 in human gastric tumor tissues (r =0.285, P <0.001)." (PMID 38344200, 2024).
giant cell tumor (1 paper, 2018). A benign, intermediate, or malignant tumor that arises from the bone or soft tissue. "In this study, the aim is to verify, by immunohistochemistry, the expression of IGF1, MDM2, STAT1, and RAC1 and investigate their potential relationship with GCT recurrence, in a large cohort of patients with a giant cell tumor of the bone." (PMID 29651441, 2018).
giant cell tumor of bone (1 paper, 2018). "In our previous study, mouse double minute 2 homolog (MDM2), insulin-like growth factor 1 (IGF1), signal transducer and activator of transcription 1 (STAT1), and Rac family small GTPase 1 (RAC1) were correlated with the recurrence of giant cell tumor of bone (GCT)." (PMID 29651441, 2018).
H1N1 virus infection (1 paper, 2016). "Moreover, we infected A549 cells with the wt H1N1 and NS1− H1N1 viruses, immunoprecipitation of Rac1 only detected in wt virus but not NS1− H1N1 virus infection, which indicated that the NS1 protein directly interacted with the cellular Rac1 protein." (PMID 27869202, 2016).
hantavirus infections (1 paper, 2016). "The central importance of RhoA activation in MEC permeability further suggests therapeutically targeting RhoA, TSCs, and Rac1 as potential means of resolving capillary leakage during hantavirus infections." (PMID 27795403, 2016).
HCMV infection (1 paper, 2025). "Our study highlighted the distinct profiles of the Rho family GTPases-Cdc42, Rho-A, and Rac1 following HCMV infection, especially in the context of IL-8/CXCR2 signaling." (PMID 40353220, 2025). "When infected HTMC cells were assessed for Rho family low molecular weight G protein by activation assays, our results showed that HCMV infection activated Cdc42 and Rac1." (PMID 40353220, 2025). "We have analyzed the activation profiles of Cdc42, Rho-A, and Rac1 after HCMV infection." (PMID 40353220, 2025). "Our findings emphasize the unique contributions of the coordinate activation of Cdc42 and Rac1, especially in CXCR2 and CCR2-mediated activation after HCMV infection." (PMID 40353220, 2025). "HCMV infection also induced cell contraction that was dependent on CXCR2, but not on CCR2, and it involved the activation of Rac1/Cdc42." (PMID 40353220, 2025).
human papillomavirus infection (1 paper, 2022). "Similarly, activation of the transcription factor NF-κB, involving the small GTPase Rac1, was required for IL-6 production and subsequent STAT3 activation in human papillomavirus infection, indicating that link between NF-κB and IL-6 might be a common feature of DNA viruses." (PMID 35458402, 2022).
hydronephrosis (1 paper, 2022). Collection of urine in the renal pelvis that results in dilatation of the renal pelvis and calyces. "Here, we demonstrated that a defect of Rac1 signaling impairs the postnatal development of renal papilla, leading to dysplasia without hydronephrosis." (PMID 36434091, 2022).
hyperandrogenization (1 paper, 2014). "We conclude that hyperandrogenization (PCOS) by DHEA diminishes ovarian Rac1 and Vav expression and activity along with an increase in expression of Caveolin1." (PMID 24628852, 2014).